H19 (H19 imprinted maternally expressed transcript)
Diseases named in the same sentence as H19 in open-access papers (continued):
Sharing a sentence is not in itself a finding about the gene and the disease.
breast cancer (continued). "A representative example of ceRNA-mediated drug resistance to targeted chemotherapy is the interaction between the lncRNA H19 and the tumor suppressive miR-200a in breast cancer." (PMID 39403602, 2024). "H19 is a gene for a long noncoding RNA, that has been reported to play a significant role in various human tumors, including breast cancer, colorectal cancer, pancreatic cancer, and GC6–10." (PMID 37821504, 2023). "In breast cancer, Peng F. and co-authors provided a picture of the lncRNA H19 as deeply embedded in a signalling axis needed to reprogram breast cancer stem cells under hypoxia." (PMID 36768150, 2023). "For breast cancer, both tumour tissue and plasma H19 expressions were increased compared to healthy controls." (PMID 37189829, 2023). "has noted an increased level of long non-coding RNA H19 in EVs derived from adriamycin-resistant breast cancer cells compared to control cells." (PMID 37534210, 2023). "Ablation of PDK1 prevented H19-mediated glycolysis in breast cancer stem cells, and H19 knockdown reduced PDK1 expression through the let-7/HIF-1 axis in hypoxia." (PMID 37821504, 2023). "Although the possible involvement of H19 in cancer chemotherapy responses has previously been suggested, definite evidence along with the mechanism by which H19 promotes DNA damage repair in breast cancer has been provided herein." (PMID 37298108, 2023). "Increased expression of H19 is correlated with disease progression and with a poor prognosis in breast cancer." (PMID 37298108, 2023). "Higher plasma levels of pre-miR-675 and its precursor H19 lncRNA in the breast cancer patients indicate an interplay between both miRNA and lncRNA." (PMID 37624037, 2023). "Knockdown of H19 was found to provide an alternative therapeutic strategy for ERα+ drug-resistant breast cancer." (PMID 36672487, 2023). "In various tumours, including breast cancer, H19 has been documented to exhibit anomalous overexpression, facilitating tumor cell proliferation, migration, invasion and the induction of EMT." (PMID 37837401, 2023). "This study aims to investigate the relative quantification of long non-coding RNA (lncRNA) H19, microRNA (miR) 675-5p, 675-3p, and miR-let 7 in breast cancer patients." (PMID 36831100, 2023). "Another study observed that H19 was overexpressed in tamoxifen-resistant breast cancer cells, and the knockdown of lncRNA H19 abrogated autophagy by decreasing LC3-II and Beclin-1 levels." (PMID 36899946, 2023). "Another study demonstrated the involvement of H19 in the symmetric division of breast cancer stem-like cells (BrCSCs), which resulted in increasing levels of self-renewing." (PMID 36674656, 2023). "Exosomal H19 promotes Dex resistance in breast cancer, and exosomal SNHG7 promotes docetaxel resistance in lung adenocarcinoma." (PMID 36816365, 2023). "According to the results, the blood levels of SPRY4‐IT1, XIST, and H19 lncRNAs have excellent potential in discriminating breast cancer from the healthy controls." (PMID 36274054, 2023). "In the present study, the dramatic rise in the circulating SPRY4‐IT1, and H19 LncRNAs expression levels are shown in breast cancer patients compared to healthy individuals." (PMID 36274054, 2023). "The correlation of H19 expression with the clinicopathologic features of breast cancer was further examined using The Cancer Genome Atlas (TCGA) dataset." (PMID 37298108, 2023). "On the other hand, the dramatic rise in the circulating SPRY4‐IT1, and H19 LncRNAs expression levels are shown in breast cancer patients compared to healthy individuals." (PMID 36274054, 2023). "In line with this, lncRNA H19 is found to be highly enriched in breast cancer cell lines and tumor tissues that are resistant to tamoxifen, and H19 knockdown in tamoxifen-resistant models results in a resensitization to tamoxifen." (PMID 37190065, 2023). "H19 expression was greatly upregulated in doxorubicin-resistant breast cancer cells (MCF-7) and its KD sensitizes them to chemotherapy." (PMID 37680988, 2023).
breast cancer (continued). "Metastatic breast carcinoma cells transmit H19 long noncoding (lnc) RNA to lung epithelial cells through exosomes." (PMID 37254190, 2023). "Exosome-mediated transfer of long noncoding RNA H19 was used to generate resistant breast cancer cells to doxorubicin." (PMID 36276272, 2022). "In this study, exosome-mediated transfer of long noncoding RNA H19 was used to generate doxorubicin-resistant breast cancer cells, and the expression of miR-3613-5p was significantly increased in these cells." (PMID 36276272, 2022). "Curiously, in ERα + breast cancer, H19 modulates resistance of PTX at both transcriptional and post-transcriptional levels." (PMID 35955440, 2022). "Studies have shown that H19 overexpression promotes the tumorigenic properties of breast cancer cells in vivo." (PMID 34644456, 2022). "In breast cancer, it was discovered that lncRNA 91H, which is transcribed from the antisense orientation of H19, promotes oncogenesis by masking methylation site on the H19 promoter, inducing the oncogenic H19 overexpression." (PMID 35292092, 2022). "In this review, we analyze the role of lncRNA H19 impairing chemo and radiotherapy in tumorigenesis, including breast cancer, lung adenocarcinoma, glioma, and colorectal carcinoma." (PMID 35955440, 2022). "In breast cancer, the 91H lncRNA is in charge of preserving the genomic imprinting of the H19/IGF2 locus by preventing histone and DNA methylation on the maternal allele." (PMID 36212140, 2022). "Emerging evidence suggests that lncRNA is closely related to drug resistance of human cancers, for example, H19 was upregulated in breast cancer and high H19 conferred cancer cell resistant to doxorubicin." (PMID 35037556, 2022). "Increased expression of long-stranded ncRNA H19 in adriamycin-resistant breast cancer cells compared to the corresponding parental cells reduced cell viability and colony formation capacity and induced apoptosis." (PMID 36203417, 2022). "It was found that the amounts of ferritin were negatively correlated with H19/miR675 levels in K562 cells (the first human established myelogenous leukemia cell line), but positively related in breast cancer cell line MCF7 cells." (PMID 36246634, 2022). "H19 is involved in breast cancer cell growth, metastasis, and multiple drug resistance in different ways." (PMID 36246634, 2022). "In an in vitro experimental model, H19 can stimulate the proliferation of breast cancer cells and inhibit apoptosis." (PMID 35506202, 2022). "Plasma levels of H19 in breast cancer, and H19, HOTAIR, and MALAT1 in gastric cancer have shown high diagnostic potential, while single nucleotide polymorphisms in the H19 gene have applications in cancer risk prediction." (PMID 35892331, 2022). "For example, it has been reported that the expression of lncRNA H19 was considerably upregulated in tamoxifen-resistant breast cancer cell line and tumor tissues, and knockdown of H19 enhanced the sensitivity to tamoxifen both in vitro and in vivo." (PMID 35810299, 2022). "There are several cancers with abnormal expression of H19: breast cancers, pancreatic cancers, choriocarcinomas, hepatocellular carcinomas, ovarian cancers, and so on." (PMID 36246634, 2022). "For example, H19 has been shown to possess oncogenic properties in multiple cancers such as colorectal cancer, breast cancer and hepatocellular carcinoma, whereas in human rhabdoid cancers, H19 displays tumour-suppressive roles." (PMID 36230680, 2022). "According to Li and co-workers, lncRNA H19 also promoted breast cancer growth through H19/miR-152/DNMT1 axis." (PMID 36685962, 2022). "Associated with EZH2, H19 can downregulate the pro-apoptotic gene BIK and NOXA to inhibit apoptosis in ERα+ breast cancers." (PMID 36246634, 2022).
breast cancer (continued). "Then we identify the drug resistant roles played by H19 in various cancers, such as breast cancers, hepatocellular carcinoma, bladder cancers, lung cancers, etc., Meanwhile, the possible association between H19 and various types of drugs is summarized." (PMID 36246634, 2022). "Increased expression of H19 is required for the acquisition of DOX-resistance in several breast cancer cell lines." (PMID 35955440, 2022). "The efficacy of chemotherapy, endocrine therapy, and targeted therapy are all influenced by the expression of H19, especially in breast cancer, liver cancer, lung cancer and colorectal cancer." (PMID 36246634, 2022). "Another study has also confirmed the H19 is over expressed in doxorubicin-resistant breast cancer cell subline compared with the matching parental cells." (PMID 36246634, 2022). "A specific lncRNA, H19, has even been highlighted as a major mediator in breast cancer chemoresistance after DOX treatment." (PMID 35415316, 2022). "Clinically, H19 was upregulated in breast cancer tissues compared to normal tissues (5-fold) and its expression correlated with poor overall survival." (PMID 36429127, 2022). "Accumulating studies showed that H19 serves as an oncogenic role and was upregulated in many malignancies, including breast cancer, ovarian cancer, lung cancer, and pancreatic cancer." (PMID 36104825, 2022). "In this regard, they uncovered that lncRNA H19 acts as a miRNA let-7 sponge and has a key role in the progression of breast cancer." (PMID 36230935, 2022). "To date, the oncogenic roles and molecular mechanisms of H19, a maternally imprinted gene, have been extensively studies in multiple cancers, including glioma, breast cancer, and lung cancer, etc.33–35." (PMID 34880375, 2021). "The downregulation of the top ranked first H19 significantly reduced breast cancer clonal formation and anchored independent growth." (PMID 34490041, 2021). "There is evidence that reduced expression of lncRNA H19 leads to inhibition of tumor growth in breast cancer, bladder cancer and colorectal cancer." (PMID 34150620, 2021). "For example, the long noncoding RNA H19, normally expressed during ESC differentiation, competitively sponges let-7 microRNAs in breast cancer cells (MDA-MB-231 and SK-BR-3 cells), causing an increase in LIN28 expression." (PMID 34439740, 2021). "lncRNA H19 overexpression significantly promotes breast cancer cell clonogenicity, migration, and mammosphere-forming ability, while lncRNA H19 knockdown markedly inhibits tumor growth and suppresses tumorigenesis in nude mice." (PMID 33656053, 2021). "It has been reported that lncRNA H19 induces the tamoxifen-resistance in breast cancer through the activation of the H19/SAHH/DNMT3B axis, thereby facilitating cell autophagy." (PMID 33796128, 2021). "It has been reported that LncRNA H19 can mediate the transformation of tumor cells into mesenchyme and is significantly elevated in bladder cancer, breast cancer, and colorectal cancer." (PMID 34977870, 2021). "H19 has a pivotal role during tumorigenesis: its upregulation is observed in about 70% of breast cancer patients." (PMID 34425750, 2021). "As a molecular sponge, H19 was found to be related to let-7 in the context of breast cancer stem cells." (PMID 34150620, 2021). "miR-675 as well as its host gene H19 has been frequently observed as a cancer driver in many human malignancies such as gastric cancer, thyroid carcinoma, breast cancer and nasalpharyngeal cancer." (PMID 34409922, 2021). "It was noteworthy that H19 was overexpressed in many drug-resistant cancer cell lines, such as cisplatin-resistant ovarian cancer and doxorubicin-resistant breast cancer cells." (PMID 34199840, 2021). "Both breast cancer cell lines and samples, especially those of TNBC, have been found to harbor high expressions of lncRNA H19, which has been implicated to increased rates of metastasis and tumorigenesis." (PMID 34026654, 2021).
breast cancer (continued). "H19 has been shown to promote cell cycle progression in breast cancer, with its deletion arresting breast cancer cells in the pre‐S‐phase of the cell cycle." (PMID 33236528, 2021). "H19 is a precursor of miR-675 and both of these ncRNAs promote breast cancer metastasis via induction of EMT and features of breast CSCs, both in vitro and in vivo." (PMID 33799834, 2021). "Overexpression of H19 in breast cancer cells promoted cell proliferation and migration while H19 knockdown reduced estrogen-induced cell growth of breast cancer cells." (PMID 34946977, 2021). "In this study, we examined the involvement and the relative contribution of H19 and miR-675 in promoting breast cancer cell aggressiveness." (PMID 32610610, 2020). "Investigators reported that overexpression of lnc-H19/miR-675 enhanced the oncogenic action of breast cancer cells, and increased cell proliferation and migration in vitro and in vivo." (PMID 32219093, 2020). "Exosomal H19 is overexpressed in patients with breast cancer compared to healthy individuals and those with benign breast disease." (PMID 32924276, 2020). "Our in vitro and in vivo data suggested that H19 plays a role in the regulation of Dox-induced cell apoptosis in breast cancer." (PMID 32345117, 2020). "Our findings revealed that H19 plays a leading role in breast cancer chemoresistance development, mediated mainly through a H19-PARP1 pathway." (PMID 32345117, 2020). "A large number of clinical studies have suggested that long noncoding RNA H19 (H19) can serve as a potential biomarker for the diagnosis of breast cancer." (PMID 32345117, 2020). "In vitro data with chemoresistant cell lines showed higher H19 and lower let-7a levels, and an H19 knockdown restores chemosensitivity in breast cancer cells." (PMID 32429417, 2020). "The siRNA H19 induced a diminution of the ALDHhigh subpopulation compared to the control cells, suggesting that H19 enriched for breast cancer stem cells." (PMID 32610610, 2020). "MIR22HG was shown to competing with miRNAs with H19 and play important regulatory roles in breast cancer progression." (PMID 32127004, 2020). "Disclosing the expression pattern of H19 will provide clues for TN breast cancer diagnosis and progression." (PMID 32190687, 2020). "To confirm the higher E33 expression in breast cancer induced by diabetes, we selected four LncRNAs (H19, E33, LIPCAR, and GAS5) that have been shown to be associated with diabetes." (PMID 31907990, 2020). "Consistent with the results from breast cancer tissues, high mRNA levels of H19 were found in doxorubicin-resistant MCF-7/Dox cells compared with the doxorubicin-sensitive MCF-7 cells." (PMID 32345117, 2020). "The goal of this study was to evaluate the role of H19 in the development of doxorubicin-resistant breast cancer." (PMID 32345117, 2020). "In the present study, we determined the importance of H19 in breast cancer chemoresistance using doxorubicin as a model chemotherapeutic agent in vitro and in vivo." (PMID 32345117, 2020). "In this report, we highlight a correlation between the expression of the H19 gene and the presence of stem cell markers in a cohort of more than 5000 breast cancer clinical samples." (PMID 32610610, 2020). "H19 overexpression was observed in doxorubicin-resistant breast cancer cells, and H19 downexpression significantly decreased doxorubicin resistance by reducing cell viability and inducing apoptosis." (PMID 32345117, 2020). "This was confirmed in our breast cancer cellular lines, where triple positive and more differentiated MCF-7 cell line presented higher basal levels of H19 compared to the triple negative less differentiated MDA-MB-231 breast cancer cell line." (PMID 33335214, 2020).
breast cancer (continued). "To evaluate the role of H19 and miR-675 in this process, we studied the resistance to anoikis in breast cancer cell lines overexpressing H19 or miR-675." (PMID 32610610, 2020). "In the present study, H19 expression was significantly upregulated in breast cancer tissues compared with normal breast tissues." (PMID 32345117, 2020). "In a spontaneous metastatic mouse model of breast cancer, lncRNA H19 has been found to regulate EMT and MET by differentially functioning as a sponge for the microRNA miR-200b/b and let-7b." (PMID 32514245, 2020). "All together, these data show that both H19 and miR-675 are able to promote the migration and invasion of breast cancer cells." (PMID 32610610, 2020). "We identified the function and target of H19 in regulating chemotherapy response both in cell lines and in clinical samples, providing evidence that H19 targets PARP-1 to mediate the chemotherapeutic resistance of breast cancer cells." (PMID 32345117, 2020). "By sponging miRNA let-7, H19 forms a H19/let-7/LIN28 reciprocal negative regulatory circuit to play a critical role in the breast cancer stem cell maintenance." (PMID 32324747, 2020). "We observed that the H19 expression was significantly upregulated in chemotherapy-resistant breast cancer tissues and doxorubicin-resistant breast cancer cell lines." (PMID 32345117, 2020). "A decrease of the sphere-forming capacity was observed in the native three cell lines when H19 was knocked down with siRNA, confirming that H19 was able to enhance the sphere-forming capacity of breast cancer cells." (PMID 32610610, 2020). "Many studies have shown that H19 promotes tumor phenotypes and induces metastasis in various cancers like gastric, colorectal, bladder, renal, lung and breast cancers but, also, in glioblastoma." (PMID 32610610, 2020). "In breast cancer, H19 acts as a ceRNA that sequesters microRNA let-7, leading to the upregulation of the let-7 target gene HIF1A that encodes HIF1α protein." (PMID 33123488, 2020). "Further studies into the in vivo metastasis in various metastasis models are warranted to clarify lncRNA H19′s function in different breast cancer subtypes and in different stages of cancer progression." (PMID 32514245, 2020). "For example, in breast cancer, lncRNA RNA H19 induces autophagy activation via the H19/SAHH/DNMT3B axis, contributing to tamoxifen resistance." (PMID 33381557, 2020). "Both knockdown and overexpression of H19 were used to assess the sensitivity to doxorubicin in breast cancer cells in vitro and in vivo." (PMID 32345117, 2020). "Our findings confirmed the protumor effects of lncRNA H19 in breast cancer cells, in which depletion of lncRNA H19 significantly suppressed cell proliferation, migration and invasion." (PMID 32514245, 2020). "For example, circulating H19 has been proved to predict presurgical response to neoadjuvant chemotherapy in breast cancer, high H19 levels had poor response to neoadjuvant chemotherapy." (PMID 32345117, 2020). "We demonstrated that the tumor-promoting role of lncRNA H19 in breast cancer, especially TNBC, which is in line with many previous studies." (PMID 32514245, 2020). "We have previously shown that H19 is overexpressed in 70% of breast cancer and promotes the tumorigenic properties of cancer cells." (PMID 32610610, 2020). "H19 levels were significantly increased in the plasma of breast cancer patients compared to healthy volunteers." (PMID 33335214, 2020). "In conclusion, this work highlights the involvement and relative contribution of lncRNA H19 and miR-675 in the occurrence and development of breast cancer metastasis." (PMID 32610610, 2020). "It has been suggested that aberrant H19 expression was involved in variety of malignancies including bladder cancer, breast cancer, esophageal cancer, and RCC." (PMID 32509581, 2020).